WNT7B (Wnt family member 7B)
Diseases named in the same sentence as WNT7B in open-access papers (continued):
Sharing a sentence is not in itself a finding about the gene and the disease.
pancreatic cancer (12 papers, 2015 to 2026). "Similarly, GATA6, a tumor-suppressive transcription factor that is mutationally inactivated in pancreatic cancer, suppresses the expression of WNT7B." (PMID 36982422, 2023). "Mining databases and data obtained from assays on human specimens had shown that Fzd7 is closely associated with Wnt7b, that Fzd7/Wnt7b expression is upregulated in pancreatic cancer tissues compared with normal tissues, and its expression is negatively correlated with survival." (PMID 33934523, 2021). "Based on the data from CCLE, we analyzed the correlation between the expression of Fzd7 and different Wnt proteins in various pancreatic cancer cell lines, and found that Wnt7b was more significantly associated with Fzd7 compared with other Wnt proteins relatively." (PMID 33934523, 2021). "Protein expression of Fzd7/Wnt7b in pancreatic cancer tissues is a prerequisite for further biological functional studies." (PMID 33934523, 2021). "As receptors and ligands, Fzd7 and Wnt7b were co‐expressed in the immunohistochemical staining of pancreatic cancer tissues to different degrees." (PMID 33934523, 2021). "FZD7/WNT7b signaling have been identified as contributors to chemoresistance in pancreatic cancer.These genes were both elevated in Panc320 following treatment with ETC-159 and paclitaxel and may explain the persistent growth rate." (PMID 38598488, 2024). "Wnt7B knockdown inhibits pancreatic cancer stem cell proliferation." (PMID 36497264, 2022). "Fzd7/Wnt7b is an important regulator of the stemness and drug resistance of pancreatic cancer cells, which may be due to PCSC subset regulation." (PMID 33934523, 2021). "The WNT7B gene may play important roles in the development and progression of gastric cancer, oesophageal cancer and pancreatic cancer." (PMID 27704726, 2017). "However, Wnt7b can mediate high levels of autocrine canonical Wnt/β-catenin activity in pancreatic cancer as well as an anchorage-independent growth phenotype." (PMID 25999350, 2015). "Therefore, we hypothesized that Wnt7b was an important ligand which exhibited synergistic action with Fzd7 in living pancreatic cancer cells." (PMID 33934523, 2021). "Therefore, the levels of Fzd7/Wnt7b may be an important factor that can regulate the proportion of CSC subsets in pancreatic cancer cells." (PMID 33934523, 2021). "For instance, WNT7B and FZD7 have been found to be overexpressed on both the RNA and protein level in gemcitabine-resistant pancreatic cancer cell lines." (PMID 36982422, 2023). "Of note, a previous study found that in ex vivo culture of pancreatic tumor organoids, downregulation of GATA6 promoted the expression of cancer cell–derived Wnt ligands, e.g., WNT7B, making some of these organoids “exogenous Wnt”-independent." (PMID 35536676, 2022). "It is currently believed that CSCs are more resistant to chemotherapy than normal tumor cells; Our previous study also showed that FZD7 can synergize with Wnt7b to increase the proportion of PDAC CSCs and enhance drug resistance of pancreatic cancer cells." (PMID 35854234, 2022). "The upregulation of WNT7B allowed cells to bypass this dependency through autocrine WNT7B signaling, consistent with previous reports that Merlin restrains WNT/β-catenin signaling via FOXM1 in pancreatic cancer." (PMID 41480769, 2026). "Correlation analysis between Fzd7 and Wnt7b in the R2 database and CCLE was performed, and the results showed that there was significant positive correlation between the expression of the two proteins in pancreatic tumors." (PMID 33934523, 2021).
gastric cancer (10 papers, 2017 to 2026). A primary or metastatic malignant neoplasm involving the stomach. "WNT7B is part of a pathway for embryonic developmental processes and is linked to carcinogenesis and cancer development, in particular, gastric cancer." (PMID 38157018, 2024). "Co-expression genes are involved in the development of multiple cancers, for example, high expression of SMR3A suggests poor prognosis in patients with head and neck squamous cell carcinoma, and WNT7B promotes gastric cancer progression and metastasis." (PMID 35350563, 2022). "FOS gene and Wnt family member 7B (Wnt7B) were found to be enriched in the Wnt signaling pathway in gastric cancer." (PMID 33373316, 2020). "Furthermore, our study showed that WNT7B is a putative ligand for FZD5 in gastric cancer." (PMID 33618713, 2021). "WNT7B-m6A-TCF7L2 positive feedback loop could promote gastric cancer progression and metastasis." (PMID 34026852, 2021). "In gastric cancer, the expression of TCF7L2 was upregulated, promoting the progression of gastric cancer by forming a positive feedback loop with Wnt7B." (PMID 39060928, 2024). "Moreover, Serum levels of WNT7B are higher in gastric cancer patients with lymph node metastasis than in gastric cancer patients without lymph node metastasis, and the level of serum WNT7B was positively correlated with the progression and metastasis of GC." (PMID 38952556, 2024).
cervical cancer (8 papers, 2020 to 2026). A primary or metastatic malignant neoplasm involving the cervix. "WNT7B has been identified as a critical factor in the progression of several cancers, including cervical cancer (CC)." (PMID 40508156, 2025). "HPV oncoproteins have been suggested to regulate the WNT signaling pathway such as elevating WNT7B mRNA in cervical cancer." (PMID 35850748, 2022). "A previous study uncovered the tumor-promoting effect of TMED5 on the malignant development of cervical cancer by activating the Wnt7b/β-catenin signaling pathway." (PMID 34404391, 2021). "Overexpression of miR-G-1 inhibited the expression of Wnt7b, and then inhibiting cell proliferation, cell cycle progression, migration, invasion, and drug resistance in cervical cancer cells." (PMID 32711579, 2020). "In addition, a study had also shown that TMED5 could interact with WNT7B in HeLa cells to activate the wnt/β-catenin pathway in cervical cancer." (PMID 35281863, 2022). "Meanwhile, TMED5 plays a tumor-promoting role in the malignant development of cervical cancer by activating the Wnt7b/β-catenin signaling pathway, while Mir-183-5p can directly target TMED5 and inhibit its expression, so as to inhibit the occurrence of cervical cancer." (PMID 34911543, 2021).
lung carcinoma (8 papers, 2019 to 2025). "GATA4 probably suppresses lung cancer through the TGF-β2/Wnt7B signalling pathway, and GATA deficiency blunted the therapeutic effect of MEK1/2 inhibition in a mouse model." (PMID 35936012, 2022). "Furthermore, whether EGFR/ERK1/ERK2 or WNT1/WNT5A/WNT7B gene expression was potentially associated with the OS of lung cancer patients was assessed by Kaplan-Meier curve and Log-rank test." (PMID 34122668, 2021). "For instance, in lung cancer cell lines and transgenic mouse models, WNT7B was shown to be the downstream effector of a GATA4–TGFB2 signaling axis which mediates cell senescence." (PMID 36982422, 2023). "Another example is that the transcription factor and known tumor suppressor GATA4 inhibits WNT7B expression via TGF-β signaling in murine lung cancer models." (PMID 36982422, 2023). "Since GATA4 induces lung cancer cell senescence through downregulating WNT7B, we checked PML-HIRA colocalization signal triggered by ectopic expression of GATA4." (PMID 30971692, 2019). "Our model predicts that GATA4 expression level is inversely correlated with those of TGFB2 and WNT7B in lung cancer." (PMID 30971692, 2019). "Our above data have shown that GATA4 expression downregulated TGFB2 and the ensuing downstream WNT7B signaling in A549 lung cancer cell line." (PMID 30971692, 2019). "By downregulating TGFB2 level via miRNAs, GATA4 decreases expression of WNT7B to induce senescence in lung cancer cells." (PMID 30971692, 2019). "Together, these data showed that TGF-β2 functioned upstream of Wnt-7b in mediating GATA4-induced senescence of lung cancer cells." (PMID 30971692, 2019). "TGF-β2 signals through TGFBR1, TGFBR2, SMAD2, and SMAD4 to upregulate WNT7B mRNA expression in lung cancer cells." (PMID 30971692, 2019). "Other genes, such as PTH2, TBR2, WNT7B, and CER1, either have similar effects shared with their homologues or have been independently reported to be associated with lung cancer at different omics levels." (PMID 35155435, 2022). "Conversely, knockdown of GATA4 expression level upregulated TGFB2 and WNT7B transcription in lung cancer cell line H226, supporting that GATA4-TGF-β2-Wnt-7b signaling axis is common to lung cancer cells." (PMID 30971692, 2019). "Knockdown of WNT7B in lung cancer cell lines could phenocopy the senescence-inducing effect of ectopic GATA4 expression, while WNT7B overexpression could rescue this effect." (PMID 36982422, 2023). "However, this actually fitted our conclusion more favorably: GATA4 is inactive and at the same time WNT7B and TGFB2 is hyperactive in lung cancer cells." (PMID 30971692, 2019). "We also found significant negative correlation of expression level between GATA4 and TGFB2 and between GATA4 and WNT7B among non-manipulated lung cancer cell lines and normal lung epithelial cell lines." (PMID 30971692, 2019). "GATA4 is an important tumor suppressor in lung cancer and could induce the senescence of lung cancer cells via upregulating several miRNAs that target TGFB2 mRNA and ensuing downregulation of WNT7b expression, suggesting WNT7b may play a carcinogenic role in lung cancer." (PMID 37486552, 2023). "Interestingly, we found that GATA4 expression resulted in similar level of PML-HIRA colocalization to that found in WNT7B knockdown, suggesting that mechanism revealed by Adams and colleagues may apply to GATA4 induced senescence in lung cancer cells." (PMID 30971692, 2019).
hepatocellular carcinoma (7 papers, 2022 to 2025). A malignant tumor that arises from hepatocytes. "In hepatocellular carcinoma, TCP1 regulates cell proliferation and migration by modulating the Wnt7b/β-catenin pathway." (PMID 37416927, 2023).
idiopathic pulmonary fibrosis (7 papers, 2011 to 2025). Idiopathic pulmonary fibrosis (IPF) is a nonneoplastic pulmonary disease that is characterized by the formation of scar tissue within the lungs in the absence of any known cause. "Several Wnt Family members such as WNT5A and WNT7B play a role in fibrotic diseases such as idiopathic pulmonary fibrosis and renal fibrosis." (PMID 36421707, 2022). "Inhibition of Gli1 suppressed myofibroblast differentiation of LR-MSCs and pulmonary fibrosis, and decreased the expression of Wnt7b, Wnt10a and β-catenin." (PMID 29844390, 2018). "We reported extremely increased expression of Wnt7b/10a, Fzd9/10 and Gli1 in the differentiation of LR-MSCs and lung fibrosis." (PMID 29844390, 2018). "A higher expression of WNT7B was found in lung tissue from patients with idiopathic pulmonary fibrosis, on mRNA and protein level." (PMID 26635199, 2016). "In addition, blocking hedgehog signaling by Gli1 inhibitor could also impair pulmonary fibrosis through defecting the transcription of Wnt7b/10a which were the target genes of Gli1." (PMID 29844390, 2018). "Konigshoff and colleagues confirmed the up-regulation of WNT1, WNT7B and WNT10B, FZD2, FZD3, β-catenin, and LEF1 expression in the lungs of individuals with idiopathic pulmonary fibrosis compared to transplant donor lung." (PMID 21490961, 2011).
colorectal cancer (5 papers, 2021 to 2025). A primary or metastatic malignant neoplasm that affects the colon or rectum. "Nevertheless, the prognostic role and mechanisms underlying WNT7b in colorectal cancer development remains unclear." (PMID 33607955, 2021). "In addition, WNT7B has been shown to drive tumor proliferation and invasion through WNT/β-catenin signaling in other cancers, such as colorectal cancer and oral squamous cell carcinoma." (PMID 40508156, 2025).
osteosarcoma (5 papers, 2020 to 2022). A usually aggressive malignant bone-forming mesenchymal neoplasm, predominantly affecting adolescents and young adults. "Taken together, these studies suggested an essential role of TMPO-AS1/miR-199a-5p/WNT7B axis in osteosarcoma tumorigenesis." (PMID 34130697, 2021). "In osteosarcomas, miR-342-5p inhibits cell growth, migration and invasion, and restores sensitivity to doxorubicin through direct targeting of Wnt member 7B (WnT7b)." (PMID 34070455, 2021). "Wnt7b is highly-expressed in many cancers and aberrant Wnt7b expression contributes to the pathogenesis of several cancers, such as pancreatic adenocarcinoma, bladder cancer and osteosarcoma." (PMID 33912460, 2021). "Recently, TMPO-AS1 has been identified as a competitive endogenous RNA that promotes tumorigenesis of osteosarcoma by regulating the miR-199a-5p/WNT7B axis, which provides a potential therapeutic target for osteosarcoma patients." (PMID 33117415, 2020). "In addition, the suppression by miR-199-5p inhibitor on osteosarcoma could be rescued by WNT7B knockdown, while this effect could be further abolished by LiCl treatment (activator of Wnt pathway)." (PMID 34130697, 2021).
pancreatic adenocarcinoma (5 papers, 2019 to 2025). "It has been unveiled that Wnt7b can serve as a primary determinant of differential Wnt/β-catenin activation in pancreatic adenocarcinoma (PDAC)." (PMID 36750722, 2023). "Wnt7b is the most effective activator of the Wnt/β‐catenin pathway in pancreatic adenocarcinoma." (PMID 33934523, 2021). "Elevated WNT7B in pancreatic adenocarcinoma has been found to mediate anchorage independent growth." (PMID 31277598, 2019).
Dupuytren’s disease (4 papers, 2016 to 2021). "A previous GWAS study of Dupuytren’s disease found an association in the same genomic region of WNT7B." (PMID 34111113, 2021). "The investigators postulated that the co‐localization of β‐catenin and Wnt7b may suggest Wnt7b is the protein causing activation of the WNT pathway in Dupuytren disease." (PMID 33855203, 2021). "Of these, Wnt7b was upregulated and found in close association with both α-SMA and β-catenin expressing cells, making it a candidate pro-fibrotic mediator in Dupuytren’s disease." (PMID 26635199, 2016). "In conclusion, SNPs WNT7B rs6519955 and RSPO2 rs611744 are associated with the development of Dupuytren’s contracture: WNT7B rs6519955 TT genotype increases the chances by 3.5-fold, and RSPO2 rs611744 genotype GG appears to attenuate the likelihood of the manifestation of DC nearly twofold." (PMID 34573275, 2021). "In addition, we found a substantial upregulation of Wnt7b, which might be a mediator of pro-fibrotic Wnt signaling in Dupuytren’s disease." (PMID 26635199, 2016).
glioblastoma (4 papers, 2021 to 2025). The most malignant astrocytic tumor (WHO grade IV). "In our study on A172 glioblastoma cells, TQ regulated the expression of key components and regulators of the Wnt signaling pathway by increasing Wnt7B expression(2.2-fold) and decreasing WNT6 expression (1.6-fold)." (PMID 39874307, 2025). "Circ_000173 facilitates the proliferation and invasion of glioblastoma cells via the miR-326/Wnt7B axis." (PMID 33509213, 2021).
osteoporosis (4 papers, 2020 to 2024). A condition of reduced bone mass, with decreased cortical thickness and a decrease in the number and size of the trabeculae of cancellous bone (but normal chemical composition), resulting in increased fracture incidence. "In this study, MALAT1 sponged miR-485-5p to activate WNT7B, which was downregulated in osteoporosis model in vivo and in vitro." (PMID 36760811, 2022). "The potential therapeutic use of Wnt7b as a novel bone formation and bone resorption dual regulator in postmenopausal osteoporosis is worthy of further investigation." (PMID 34881243, 2021). "Thus, we demonstrate that Wnt7b diminishes osteoclast formation, which will be beneficial for osteoporosis therapy in the future." (PMID 34881243, 2021). "The present work therefore provides evidence that targeted delivery of Wnt7b may be a potential therapy for osteoporosis and recalcitrant fractures." (PMID 32047703, 2020). "MALAT1 promoted osteogenic differentiation and inhibited cell apoptosis through the miR‐485‐5p/WNT7B axis, which suggested that MALAT1 is a potential target to alleviate osteoporosis." (PMID 39043618, 2024). "In conclusion, MALAT1 promoted osteogenic differentiation and inhibited cell apoptosis through the miR-485-5p/WNT7B axis, which suggested that MALAT1 is a potential target to alleviate osteoporosis." (PMID 36760811, 2022). "Due to the lack of changes in the level of reduction in BV/TV, we concluded that Wnt7b achieved a beneficial effect on bone mass, rather than playing a protective effect on OVX-induced osteoporosis in vivo." (PMID 34881243, 2021).
renal fibrosis (4 papers, 2014 to 2025). A final common manifestation of a wide variety of chronic kidney diseases characterized by glomerulosclerosis and tubulointerstitial fibrosis. "We are convinced that the activation of the Wnt7b/β-catenin signaling pathway constitutes the central pivot in the development of renal fibrosis during AAN." (PMID 40432885, 2025). "We hypothesize that while Wnt7b promotes the regeneration of PCTECs, these regenerative cells display dual epithelial and mesenchymal characteristics that are related to renal fibrosis in chronic AAN." (PMID 40432885, 2025).
cholestasis (3 papers, 2022 to 2025). Impairment of the bile flow caused by obstruction within the liver, or outside the liver in the bile duct system. "Wnt7b, one of the switches driving the proliferative/inflammatory phenotype during cholestasis, could induce the proliferation of cholangiocytes in an autocrine manner and increases the secretion of pro-inflammatory cytokines." (PMID 35814252, 2022).
melanoma (3 papers, 2010 to 2017). A malignant, usually aggressive tumor composed of atypical, neoplastic melanocytes. "RNAi of candidate Wnts identifies Wnt1, Wnt2, Wnt3, and Wnt7b as the specific isoforms mediating autocrine Wnt signaling in tumor cell lines M14 (melanoma), NCI-H23 (NSCLC), PA-1 (teratocarcinoma), and Hs578T (breast), respectively." (PMID 20856934, 2010). "Although high levels of WNT2, WNT7B and WNT10B are reported to activate WNT/β-catenin signalling, several studies report a reduction in nuclear β-catenin staining in high-risk melanoma patients." (PMID 23129487, 2012).
respiratory failure (3 papers, 2008 to 2013). The significant impairment of gas exchange within the lungs resulting in hypoxia, hypercarbia, or both, to the extent that organ tissue perfusion is severely compromised. "Moreover, deficiency of Wnt7b results in postnatal death due to lung hemorrhage caused by vascular leakage and subsequent respiratory failure, similar to what we observed upon selective Prdm6 deletion in SMCs using SM22-Cre." (PMID 24278461, 2013). "Similarly, the loss of Wnt7b causes perinatal death due to respiratory failure, subsequent to impaired mesenchymal growth and vascular development that is due to defective autocrine and paracrine Wnt signaling by the airway epithelium." (PMID 18478089, 2008). "Wnt7B lacZ−/− mice exhibit lung hypoplasia and respiratory failure, and Wnt7BlacZ−/− embryos and newborn mice exhibit severe defects in the smooth muscle component of the major pulmonary vessels, suggesting that WNT7B signaling is required for proper lung mesenchymal growth and vascular development." (PMID 21490961, 2011).